PINK1-AS (PINK1 antisense RNA)
Synonyms: FLJ00387; PINK1AS; naPINK1; PINK1-AS1
Gene: Long non-coding RNA gene on chromosome 1 (20,642,657 to 20,652,193, reverse strand). Ensembl gene ENSG00000117242.
Diseases named in the same sentence as PINK1-AS in open-access papers:
PINK1-AS is named in the same sentence as 1 disease in open-access papers, as found by Europe PMC text mining. Sharing a sentence is not in itself a finding about the gene and the disease.
PINK1-AS shares sentences with these, for which no sentence is quoted: neuroblastoma (1 paper).